BRD2 (bromodomain containing 2)
Diseases named in the same sentence as BRD2 in open-access papers (continued):
Sharing a sentence is not in itself a finding about the gene and the disease.
juvenile myoclonic epilepsy (12 papers, 2008 to 2024). "BRD2 expresses multiple alternatively spliced variants, and has been implicated in juvenile myoclonic epilepsy and inflammatory bowel disease." (PMID 39336776, 2024). "DNAm of the BRD2 promotor has been implicated in juvenile myoclonic epilepsy, a common adolescentonset genetic generalized epilepsy syndrome." (PMID 36385171, 2023). "A developmental decrease in parvalbumin-positive neurons precedes the onset of increased flurothyl-induced seizure susceptibility in the Brd2+/− mouse model of juvenile myoclonic epilepsy and likely contributes to the clinical manifestations of this syndrome." (PMID 34604312, 2021). "SPG7, ATP-dependent zinc metalloprotease is involved in development of spastic paraplegia while BRD2 gene microdeletion is associated with juvenile myoclonic epilepsy development." (PMID 28423529, 2017). "Consistent with a role in neuronal development, human Brd2 has recently been identified as the major susceptibility gene for juvenile myoclonic epilepsy." (PMID 18402692, 2008). "Brd2 is also implicated in human disease states that are relevant to its role in neuronal development, including neurodegeneration following stroke, and the defective neurogenesis underlying juvenile myoclonic epilepsy (JME)." (PMID 34842711, 2021). "BRD2 is a member of the BrD subfamily, and it is linked to adolescent-onset epilepsy, known as Juvenile Myoclonic Epilepsy (JME)." (PMID 39845785, 2024). "Association analysis in human genetics using single nucleotide polymorphisms and microsatellite markers in the critical genomic region has revealed that BRD2 is a major susceptibility locus for juvenile myoclonic epilepsy (JME), a group of neurological disorders characterized by epileptic seizures." (PMID 27827996, 2016). "Brd2 facilitates expression of genes promoting proliferation and is implicated in apoptosis and in egg maturation and meiotic competence in mammals; it is also a susceptibility gene for juvenile myoclonic epilepsy (JME) in humans." (PMID 18402692, 2008). "XLOC_013392 regulated Brd2 expression, linking it to juvenile myoclonic epilepsy." (PMID 39135955, 2024). "Brd2 is a protooncogene and candidate gene for juvenile myoclonic epilepsy in humans, a homeobox gene regulator in Drosophila, and a maternal-zygotic factor and cell death modulator that is necessary for normal development of the vertebrate central nervous system (CNS)." (PMID 34842711, 2021). "In patients with juvenile myoclonic epilepsy, several individual loci are involved, of which GABRA1, GABRD, EFHC1, BRD2, CASR, and ICK with complex inheritance are considered to be the most pathogenic." (PMID 39513854, 2024).
epilepsy (10 papers, 2008 to 2025). A brain disorder characterized by episodes of abnormally increased neuronal discharge resulting in transient episodes of sensory or motor neurological dysfunction, or psychic dysfunction. "BRD2, a transcription factor previously implicated with epilepsy, was convergently upregulated following propranolol treatment in both cells (DAOY Log2FC = 2.57, q val = 1.17E−230; NPC Log2FC = 0.360, q val = 0.007; Stouffer’s Z-score = 21.13, q val = 4.56E−95)." (PMID 35927430, 2022). "In intron 2 of the BRD2 gene, a polymorphic GT repeat is strongly associated with epilepsy." (PMID 24704980, 2012). "A study investigating the link between expression of the Bromodomain-Containing Gene (BRD2) and epilepsy in humans uncovered the role of variable intronic repeats in regulating gene expression through alternative mRNA splicing pattern." (PMID 24704980, 2012). "That is, there are additional human findings, besides the genetic data, that directly connects human epilepsy to our finding of a reduction in GABAergic neurons in Brd2+/− mouse basal ganglia pathway." (PMID 21887291, 2011). "Gene expression could be also affected by the methylation status of gene promoters, as was demonstrated for epilepsy-associated genes FMR1 and BRD2 (bromodomain-containing transcriptional activator 2) in humans." (PMID 36428502, 2022). "It is interesting to note that many of the ME-harboring epilepsy-associated genes are typically reported to be dysregulated in TLE patients’ brains, for example, SCN1A, BRD2, and NF1." (PMID 34868252, 2021). "Because the evidence supports a role for BRD2 in epilepsy-related brain function, finding the biological basis for its influence on seizure susceptibility and abnormal (epileptiform) EEG traits will help elucidate the mechanisms underlying the etiology of the IGEs." (PMID 21887291, 2011). "The statistical and population evidence supports BRD2 as strongly influencing susceptibility to JME in particular and, potentially, a wider range of IGE syndromes/seizures, including photosensitivity and epilepsy-related electroencephalography (EEG) traits." (PMID 21887291, 2011). "Our study uncovers both maternal and zygotic contributions of brd2, the analysis of which may provide insight into the earliest events in vertebrate development, and the etiology of some forms of epilepsy, for which zebrafish is an important model." (PMID 18402692, 2008). "Similarly, the decision to pursue BRD2 was motivated by a family study of human epilepsy." (PMID 32559200, 2020). "Although the association of BRD2 and epilepsy is not clear, we tentatively speculate that the hypermethylation detected in BRD2 in our cohort may play a role in the occurrence of epilepsy in these patients." (PMID 31685013, 2019). "BRD2 has been associated and linked to the expression of JME in humans, this underlying susceptibility could, when another insult occurs, either environmental or genetic, lead to the expression of epilepsy." (PMID 21887291, 2011).
leukemia (10 papers, 2007 to 2025). A malignant (clonal) hematologic disorder, involving hematopoietic stem cells and characterized by the presence of primitive or atypical myeloid or lymphoid cells in the bone marrow and the blood. "Interestingly, several trx-G genes act as genetic regulators of E2F in Drosophila, and chromosomal abnormalities in the gene for trx human homolog MLL, underlie several forms of leukemia; possibly, this reflects a conserved Brd2/trx/E2F regulatory pathway." (PMID 18402692, 2008). "One candidate for a chromatin-associated factor interacting with both acetylated histones and the transcriptional machinery (TBP, RNA polymerase II) is Brd2, which was recently implicated in the regulation of STAT5 activity in leukemia cell lines." (PMID 25769527, 2015). "Here we studied the effects of OTX015 in a panel of leukemia cell lines, including the drug effects on cell growth, apoptosis and the expression of genes involved in the BRD2/3/4 signaling pathway." (PMID 25989842, 2015). "Consistent with this, transgenic mice with lymphoid-restricted overexpression of Brd2 up-regulate E2F target gene cyclin A, and develop B cell lymphoma and leukemia." (PMID 18402692, 2008). "Directed overexpression of Brd2 in mouse lymphocytes is found to develop B-cell lymphoma and leukemia." (PMID 17848202, 2007). "Overexpression of BRD2 in transgenic mice leads to B-cell lymphoma and leukemia development." (PMID 41048997, 2025). "Brd2 is a nuclear-localized serine-threonine kinase that has elevated activity in human leukemias." (PMID 17848202, 2007). "It was able to effectively stimulate the BRD2/3/4 proteins degradation in the RS4;11 leukemia cells, with DC50 values ranging from 30 to 100 pM." (PMID 38389844, 2024). "The bromodomain (BRD) and extraterminal (BET) proteins including BRD2, BRD3 and BRD4 have been identified as key targets for leukemia maintenance." (PMID 25989842, 2015). "This is in agreement with the recent demonstration that BET proteins, in particular Brd2, regulate STAT5 activity in human leukemia cells." (PMID 25769527, 2015). "Western blotting demonstrated a small increase (~1–2 fold) in the expression of total RNA-pol-II, CTD-S2P, CDK7, CDK9/P-TEFb, BRD4 and BRD2 in the 5-AZA-resistant M2AR and SCAR leukaemia cells compared to the original 5-AZA-sensitive OCI-M2 and SC leukaemia cells." (PMID 29563491, 2018).
prostate carcinoma (10 papers, 2012 to 2025). A carcinoma that arises from epithelial cells of the prostate gland. "In prostate cancer, SPOP mutations disrupt the ubiquitination process, leading to aberrant stabilization and altered expression of epigenetic regulators, including BRD2." (PMID 40432836, 2025). "The BET proteins (BRD2/3/4) are key epigenetic co-regulators mainly for prostate cancer growth, with BRD4 being a critical component of AR signaling." (PMID 40407591, 2025). "The BRD2 expression level exhibited a positive correlation to the mortality rate of prostate cancer patients." (PMID 38637684, 2024). "Our characterization of the interaction between Brd2 and H2A.Z nucleosomes also furthered our understanding of the role H2A.Z plays in promoting AR-regulated transcription in prostate cancer cells, yielding potential new molecular targets for therapy." (PMID 23144632, 2012). "Indeed, it has been shown that cells expressing prostate cancer-derived SPOP mutants are resistant to BET inhibitor due to elevated expression of BET family proteins BRD2, BRD3, and BRD432,33." (PMID 34599168, 2021). "Moreover recruitment of BRD2 to the AR regulated genes in prostate cancer has been found to be dependent on H2A.Z.145." (PMID 29116202, 2017). "Finally, the small molecule inhibitor JQ1 blocked recruitment of Brd2 to AR–regulated genes, prevented transcriptional activation of these genes, and inhibited prostate cancer cell proliferation." (PMID 23144632, 2012). "While the most consistent and pronounced effects were observed following BRD4 knockdown, loss of BRD2 and BRD3 also inhibited LNCaP cell growth, suggesting that all three BET family proteins contribute to the potent growth responses to BET inhibitors observed in prostate cancer cell lines." (PMID 24293458, 2013). "A strong overlap of the identified eight FAIRE-seq peaks was found with known players in prostate cancer including AR, FOXA1, ERG, bromodomains BRD2 and BRD3 and, interestingly, MYC." (PMID 26412853, 2015). "Besides, SPOP-mutant prostate cancers often accumulate BET proteins, including BRD2, BRD3 and BRD4." (PMID 36357379, 2022).
glioma (9 papers, 2014 to 2025). A benign or malignant brain and spinal cord tumor that arises from glial cells (astrocytes, oligodendrocytes, ependymal cells). "The present study demonstrated that glioma cells with mutated IDH1 had higher Brd2 levels and proliferated more slowly than the other two groups." (PMID 24520288, 2014). "Several BET proteins, BRD4 and BRD2, have been shown to be overexpressed in gliomas making their inhibition an emerging therapeutic strategy." (PMID 38183103, 2024). "At present, OTX015 (MK-8628), a novel BRD2/3/4 inhibitor, used to treat glioma in preclinical trials, but the therapeutic effect of BET inhibitor on glioma needs further study." (PMID 36711038, 2023). "ZBC260 promotes degradation of BRD2/3/4 in all four glioma cell lines as displayed by Western Blotting." (PMID 33093476, 2020). "In CGGA, lower expression of BRD2/BRD4 and higher expression of BRD3 in the primary glioma datasets was associated with survival superiority of patients." (PMID 33135348, 2020). "In this study, IDHI mutation resulted in an increased proportion of cells in the G1 phase and increased Brd2 levels in glioma cells." (PMID 24520288, 2014). "Gliomas have significantly higher BRD2 and BRD4 levels than control tissues, and the mRNA and expression levels of BRD4 are closely related to the tumor subtypes and the overall survival rate of the patients, indicating that I-BET151 can have a therapeutic effect on gliomas." (PMID 34540687, 2021). "Two BET proteins, BRD2 and BRD4, are significantly overexpressed in gliomas, and the knockout of BRD4 diminishes glioma proliferation." (PMID 38183103, 2024). "A total of 680 TCGA RNA‐s Equation (TCGA‐seq) samples and 281 CGGA RNA‐s Equation (CGGA‐seq) samples were evaluated to investigate the relation between mRNA expression of BET family members BRD2/BRD3/BRD4, and overall survival (OS) in glioma patients." (PMID 33135348, 2020). "BRD2 expression levels did not correlate with a significant increase or decrease in overall survival in either IDHwt or IDHmut glioma patients." (PMID 35467128, 2022). "Therefore, it seems that BRD2/BRD3 has no value in targeted glioma therapy." (PMID 33135348, 2020). "In glioma, BRD4 (and not BRD2 or BRD4) sustained the self-renewal of glioma-initiating cells by modulating the Notch1 signaling pathway, and significant inhibition of BRD4 resulted in the loss of stem cell-like properties of glioma cells." (PMID 36674511, 2023). "In recurrent glioma, BRD4 expression (P < .05), but not BRD2/BRD3 expression (P > .05), resulted in significant differences in OS." (PMID 33135348, 2020). "BETi JQ1 demonstrated significant inhibition of BET activity but limited clinical success, as seen with the withdrawal of the Phase II trial for birabresib (MK-8628, OTX015), a selective inhibitor of BRD2/BRD3/BRD4, due to lack of efficacy in IDH-wildtype gliomas." (PMID 40565099, 2025). "Here, we validated that BRD4, not BRD2 or BRD3, has value in targeted glioma therapy." (PMID 33135348, 2020). "We evaluated BRD4, not BRD2 or BRD3, has value in targeted glioma therapy." (PMID 33135348, 2020).
Insulin resistance (9 papers, 2017 to 2022). Increased resistance towards insulin, that is, diminished effectiveness of insulin in reducing blood glucose levels. "Brd2 binds not only activators like E2F proteins, Hats and Hdacs (histone deacetylases) to regulate the expression of diverse genes, Brd2 normally function is to inhibit adipogenic differentiation and is linked to insulin-resistance and cancer." (PMID 29284058, 2017). "Myeloid lineage-specific BRD4 knockout mice fed a high-fat diet display reduced local and systemic inflammation and improved insulin sensitivity, while overexpression of BRD2 in white adipose tissues from wild-type mice induces insulin resistance." (PMID 36015180, 2022). "BRD2 has been reported to play a key role in inflammatory response in murine macrophages and in inducing insulin resistance." (PMID 35986286, 2022). "ERK signaling can upregulate bromodomain-containing protein 2 (Brd2), a nuclear serine/threonine kinase, during adipocyte differentiation, generating insulin resistance." (PMID 34069890, 2021). "In addition, BRD2 suppresses Deptor expression, thereby activating the mTORC1 pathway, leading to feedback inhibition of insulin signaling and promoting insulin resistance." (PMID 36015180, 2022). "In addition, reductions in BRD2 blocks insulin resistance even in severely obese mice." (PMID 36015180, 2022). "This is because BRD2 knockdown attenuates TNF-α-mediated inflammatory mRNA expression in adipocytes, indicating that BRD2 is required for TNF-α signaling and the initiation of insulin resistance in vitro." (PMID 36015180, 2022). "BRD2 and BRD4 regulate the body’s energy-providing genes, such as the β cells of the pancreas, and knockdown or decrease the expression of BRD2 improving β-cell function by increasing insulin secretion and protects the cells from insulin resistance." (PMID 35401196, 2022).
lymphoma (7 papers, 2013 to 2025). A malignant (clonal) proliferation of B- lymphocytes or T- lymphocytes which involves the lymph nodes, bone marrow and/or extranodal sites. "Finally, Eμ-BRD2 transgenic mice over-expressing BRD2 in the B-cell compartment, develop aggressive B-cell leukemias and lymphomas resembling DLBCL with an ABC phenotype." (PMID 36046113, 2021). "Recent reports describe a role for several members of the bromodomain and extraterminal (BET) protein family, including bromodomain-containing proteins BRD2, BRD3 and BRD4, in the maintenance of aberrant chromatin states in AML, ALL, myeloma and lymphoma." (PMID 25989842, 2015). "More recently, inhibition of BRD2 by siRNA knockdown or treatment with JQ1 was shown to inhibit constitutive STAT5 activity in a large panel of acute leukemia and lymphoma cell lines." (PMID 25989842, 2015). "This is consistent with previous findings that IBET preferentially targets BRD4 over BRD2 and BRD3, and that lymphoma Raji cells stably expressing a dominant negative BRD4 displayed near identical global effects on gene expression to those treated with the BET inhibitor JQ1." (PMID 38884356, 2024). "In these lymphoma lines, it thus seems that JQ1 treatment regulates CYCLON indirectly through MYC rather than through BRD4 – or indeed through BRD2 and 3 which JQ1 can also inhibits." (PMID 23828858, 2013).
glioblastoma (6 papers, 2015 to 2025). The most malignant astrocytic tumor (WHO grade IV). "Six of these transcripts were overexpressed in recurrence, including the bromodomain gene BRD2 (padj = 9.3 × 10−3), thought to be essential to glioblastoma cell cycle maintenance and an emerging therapeutic target." (PMID 36765632, 2023). "BET protein is also necessary for the proliferation of glioblastoma cells, BRD2 and BRD4 mRNA are significantly overexpressed in glioblastoma cells." (PMID 36711038, 2023). "BET proteins are also required for glioblastoma cell proliferation, mRNA of BRD2 and BRD4 are significantly overexpressed in glioblastoma, while disruption of BRD4 expression reduced glioblastoma cell cycle progression." (PMID 25849938, 2015).
type 2 diabetes (6 papers, 2013 to 2021). "For example, one study in mice found that extremely obese mice with a mutation in the Brd2 gene are protected from developing type 2 diabetes mellitus." (PMID 24400816, 2014). "In animal studies, it has been shown that mutations in Brd2 gene could prevent type 2 diabetes in mouse." (PMID 31795992, 2019).
COVID-19 (5 papers, 2020 to 2022). A disease caused by infection with severe acute respiratory syndrome coronavirus 2. "These proteins include the COVID-19 Main Protase (MPro), Receptor binding domain of spike protein, Nucleocapsid, or the N-protein and host Bromodomain protein (BRD2)." (PMID 33478471, 2021). "Similarly, it has been suggested that BRD2 inhibitors can potentially block where COVID-19 envelop protein E binds and could be used as drug targets for COVID-19." (PMID 33478471, 2021). "It should be noted that BRD2/BRD4 are potential drug targets of Envelope (E) protein, a structural proteins of COVID-19, which plays a central role in virus morphogenesis and assembly." (PMID 33082858, 2020). "Together, our results pinpoint BRD2 as a potent and essential regulator of the host response to SARS-CoV-2 infection and highlight the potential of BRD2 as a novel therapeutic target for COVID-19." (PMID 33501440, 2021).
colorectal cancer (4 papers, 2022 to 2025). A primary or metastatic malignant neoplasm that affects the colon or rectum. "One study of colorectal cancer reported that LAMB3 overexpression was activated by BRD2/acetylated ELK4 complex; furthermore, LAMB3 overexpression activated AKT and resulted in degradation of FOXO3/4, a tumor suppressor protein." (PMID 38473784, 2024). "In previous studies, LAMB3 was also reported to promote tumor progression and chemoresistance through the AKT-FOXO3/4 axis and be transcriptionally regulated by the BRD2/acetylated ELK4 complex and polymeric immunoglobulin receptor in colorectal cancer." (PMID 36612197, 2022). "HCT116 (colorectal cancer) was included as an out-of-lineage control, and JQ1, an established potent inhibitor of BET family proteins BRD2, 3, 4, was included as an inhibitor of bromodomain proteins with a distinct selectivity profile." (PMID 35853853, 2022).